IL5 (interleukin 5)
Diseases named in the same sentence as IL5 in open-access papers (continued):
Sharing a sentence is not in itself a finding about the gene and the disease.
nasal polyps (continued). "Similarly, nasal polyp tissue displays a SEB-stimulated significant release of IL-1, TNFα, IFN-γ, IL-2, IL-5 and IL-17." (PMID 25875480, 2015). "Spontaneous release of IL-5, and TNF-α could be observed in nasal polyp tissue, which was significantly inhibited by the combination of S. baicalensis and E. senticosus, but no single component, at a concentration of 2 μg/mL of each component (data not shown)." (PMID 22272213, 2012). "After 18 hours, SEB significantly induced the release of TNF-α, IFN-γ, IL-2, and IL-5 in both nasal polyp-asthma groups compared with healthy controls but without statistical differences between disease groups." (PMID 23282714, 2010). "Therefore, the higher expression of P-gp in nasal polyps could be related to the hypersecretion of TSLP and IL-5 in CRSwNP patients." (PMID 35264183, 2022). "Interestingly, the presence of nasal polyps in one of nine patients belonging to the IL-5-negative Cluster-1 demonstrates that the CRSwNP phenotype is not always associated with type-2 endotype, which is of clinical importance when planning biologic therapies." (PMID 35455762, 2022). "In a previous study, despite the small number of patients, they carefully suggested that the profile of a true super-responder to long-term anti-IL-5 biologics was an adult with a relatively short duration of eosinophilic asthma, without nasal polyps, chronic airflow limitation, or overweight." (PMID 35055384, 2022). "However, IL-5-producing ILC2s are almost absent in nasal polyps from cystic fibrosis patients (CFwNP)." (PMID 36052086, 2022). "In consequence, anti-IL-5 mAb therapy may have benefits controlling sinonasal symptoms also in patients without nasal polyps." (PMID 36498632, 2022). "Nasal polyps might be a marker of more significant treatment effect of anti-IL5 therapy when compared to eosinophilic asthma without nasal polyps." (PMID 32467765, 2020). "The anti-IL-5 antibody mepolizumab was approved in November 2021 as an add-on therapy to intranasal glucocorticosteroids for the treatment of adults with severe chronic rhinosinusitis with nasal polyps when systemic glucocorticosteroids or surgery do not provide adequate disease control." (PMID 38549814, 2024). "We also showed in the same year that nasal polyp eosinophils in tissue have a longer survival time compared to blood eosinophils and that anti-IL-5, but not anti-IL-3 or anti-GM-CSF could induce apoptosis in tissue eosinophils, being confirmed in human disease today." (PMID 31452831, 2019). "There were also significant increases in GATA3, IL4, IL5, and IL17 gene expression levels in nasal polyp tissue from the AERD group compared with the non-AERD group." (PMID 38360807, 2024). "The aim of the study was to determine the expression of IL-5, POSTN and IL-33, at the gene and protein levels, in eosinophilic CRS with nasal polyps (CRSwNP) and without nasal polyps (CRSsNP), and to correlate this expression with clinical severity." (PMID 35752781, 2022). "Polycytidylic acid (poly (IC)) is the ligand for TLR3, and exposure to poly (IC) selectively induces IL-10, but not IL-5, IL-13, IFN-γ or IL-17A, production by nasal polyp cells." (PMID 36003393, 2022). "Anti-IL5- and anti-IL-5R biologics such as benralizumab and TPI ASM8 have not been used in nasal polyposis, but a DBPC phase 3 study to evaluate benralizumab in patients with CRSwNP is currently being completed (OSTRO study)." (PMID 33426426, 2021). "Immunoglobulins like IgA, IgE, IgG and IgM are also increased in polyp fluid and tissue and the concentrations of total IgE, IL-5, eotaxin, ECP, LTC4/D4/E4, and sCD23 were significantly higher in nasal polyp tissue as compared with non-polyp tissue." (PMID 25379119, 2014).
nasal polyps (continued). "Ethmoid sinus mucosa of CRSwNP patients showed significantly increased expression of interleukin (IL)-5, eosinophil-cationic protein, immunoglobulin E (IgE), and Staphylococcus enterotoxin (SAE)-IgE compared with chronic rhinosinusitis without nasal polyp (CRSsNP) patients." (PMID 28464955, 2017). "However, ECRS patients showed significant upregulation of IL-5 mRNA compared with non-ECRS patients in all sinonasal regions, with the increase being more prominent in the frontal recess and nasal polyps." (PMID 28464955, 2017). "The overproduction of IL-5 might intensify eosinophilic inflammation in aspirin-sensitive patients and is correlated to increased levels of IgE and Staphylococcus aureus enterotoxins(SAE) present in nasal polyp tissue but is not specific for patients suffering from CRSwNP and aspirin sensitivity." (PMID 22927869, 2012).
COVID-19 (134 papers, 2020 to 2025). A disease caused by infection with severe acute respiratory syndrome coronavirus 2. "Supporting this, CSF analysis in several COVID-19-associated ON patients revealed elevated levels of IL-5, IL-6, and IL-8, indicating enhanced innate immune activity." (PMID 40728559, 2025). "Within this set, there are several immune-related processes known to be implicated in COVID-19 severity such as ‘Interleukin-5 and interleukin-13 signalling’ and ‘Caspase activation via death receptors in the presence of ligand’." (PMID 38527092, 2024). "Increased BAL IL-13, IL-5, and eotaxin at day 5 suggest increased activation and recruitment of eosinophils which have been implicated in COVID-19 pathogenesis." (PMID 38259435, 2023). "Serum 25(OH)D, IL-5 and Eos levels together had a better diagnostic value (AUC = 0.820) for COVID-19 severity than any indicator alone." (PMID 37705107, 2023). "Serum 25(OH)D levels (OR = 0.987, 95% CI = 0.998–0.977, P = 0.022) and IL-5 (OR = 1.207, 95%CI = 1.327–1.098, P = 0.000) were strongly associated with COVID-19 severity." (PMID 37705107, 2023). "Results from the current study show that serum IL-5 expression is an independent risk factor for the severity of COVID-19." (PMID 37705107, 2023). "For the cytokines to critically ill COVID-19 direction, only IL5 showed suggestive association with COVID-19." (PMID 35356648, 2022). "It is predicted that hospitalised COVID-19 patients at risk of fatal outcome should be treated with anti-IL-5 drugs as soon as possible before peripheral eosinophil count falls." (PMID 33767626, 2021). "Balanced IL-4 and IL-5 responses could aid prevent exaggerated inflammation, thus reducing the risk of COVID-19." (PMID 40910046, 2025). "Severe COVID-19 seems to correlate with an early defective Th1 response linked to an increased Th2 response in the context of a cytokine dysregulation, with an increase in interleukin (IL)-13, IL-5, eotaxin-2, IgE, and eosinophils." (PMID 38541703, 2024). "In summary, mepolizumab, an anti-IL-5 monoclonal antibody used for severe eosinophilic asthma, may inadvertently increase the risk of opportunistic infections, including COVID-19, by altering the immune system dynamics." (PMID 39574910, 2024). "Our study focus on finding the association of vitamin D levels with the severity of COVID-19 in patients and whether the serum 25(OH)D status combined with IL-5 levels and Eos counts could be predict the risk of COVID-19 mortality." (PMID 37705107, 2023). "This study found that the serum 25(OH)D status combined with IL-5 levels and Eos counts could be identified as a predictive factor for recognizing the risk of COVID-19 mortality." (PMID 37705107, 2023). "Overall, CEC attributes of convalescent COVID-19 patients correlated with a vast majority of differentiation and activation factors associated with T cells and B cells (IL-4, IL-5, IL-7, IL-17A, IL-18, MIP-1α, and RANTES), implicating a broad adaptive immune response with endothelial dysfunction." (PMID 33752798, 2021). "Our finding that small subgroups of patients in our cohorts have increased IL-17A or IL-5 in serum, points to additional immunotypes that may have distinct clinical characteristics in acute infection or associate with post-recovery sequelae of long COVID-19." (PMID 35177626, 2022). "This is because IL-1α, IL-1β, IL-5, IL-8, NF-κβ, and interferons (α, β, and γ), are molecules that overlap with the immune response to COVID-19." (PMID 39941142, 2025). "Serum from patients with severe COVID-19 induced increased levels of IL-1α, IL-1Ra, IL-5, IL-6, IL-10, IL-12(p40), IL-18, IL-27, and TNF-α." (PMID 41583455, 2025). "The low levels of IL-5 suggest a reduced Th2-mediated immune response and less eosinophilic inflammation, potentially leading to better outcomes in COVID-19 patients." (PMID 40557167, 2025).
COVID-19 (continued). "Asymptomatic individuals exhibited a significantly higher expression of Th2 cytokines compared to patients with moderate and severe COVID-19, specifically IL-5 (p = 0.0444) and IL-13 (p = 0.0389)." (PMID 40266113, 2025). "The elevation of IL-5, IL-6, and IL-15 in PLWH/COVID-19 mirrors previously reported cytokine signatures associated with hyperinflammation and adverse clinical outcomes in both infections." (PMID 41516165, 2025). "There was a study showing that eosinophil-independent IL-5 levels were increased in critically ill COVID-19 patients who survived, and the same trend was present in our results." (PMID 39770705, 2024). "The inhibition of IL-5 can affect the virus resistance of COVID-19 patients, but it can also reduce hyperinflammation in ARDS models." (PMID 39770705, 2024). "Moreover, it was reported that epithelial surface bound ACE2 expression is inversely associated with the levels of Th2 cytokines (IL-4, IL-5, and IL-13) that could alleviate the viral-induced release of interferons and downregulate the cytokine storm typical of increasing COVID-19 severity." (PMID 38263182, 2024). "Consistently, we found the plasma levels of IL-5, IL-6, IL-8, IL-10 and IP-10 to be significantly higher in severe COVID-19 patients compared with control plasma." (PMID 37207201, 2023). "Serum 25(OH)D levels were able to predict the mortality of patients with COVID-19, and the predictive value was even higher when combined with IL-5 levels and eosinophil (Eos) count." (PMID 37705107, 2023). "Our findings further showed that 25(OH)D levels in the serum of patients with COVID-19 correlated negatively with the expression of IL-5." (PMID 37705107, 2023). "Serum 25(OH)D levels were negatively correlated with IL-5 in COVID-19 patients, which laid a foundation for further research on the mechanisms involved in these findings." (PMID 37705107, 2023). "The levels of 25(OH)D in the serum of patients with COVID-19 correlated negatively with the expression of IL-5, however, the potential mechanism requires further exploration." (PMID 37705107, 2023). "Circulating 25(OH)D status correlated negatively with the expression of IL-5 (r=-0.262, P < 0.001) and was positively linked with CD8+ T cell counts (r=-0.121, P < 0.05) in patients with COVID-19." (PMID 37705107, 2023). "In one study of 52 individuals infected with COVID-19, the maximum concentrations of plasma cytokines (IL-2, IL-5, IL-17, IL-8, IL-10, IL-6, IL-12p70, and IFN-γ) were found to be significantly higher in those who had died than in those who had survived." (PMID 36766961, 2023). "In the 2nd pregnancy trimester, increased ratios were observed for IL-6, IFN-γ, IL-5 and GM-CSF (3x increase) in the COVID-19 group." (PMID 37122732, 2023). "For instance, the ratios of IL-2/IL-5, IL-2/IL-10, IL-2/IL-9, IL-6/IL-5, IL-6/IL-10 and IL-6/IL-9 were considerably higher in COVID-19 ICU patients as compared to HC subjects (≈8571-, 4800-, 4444-, 378-, 521-, and 172-fold differences respectively)." (PMID 36363785, 2022). "Hematologic cancer patients that showed highly networked and coordinated anti-SARS-CoV-2 antibody production, with central importance of IL-4, IL-5, IL-12A, IL-15, and IL-17A, presented only mild COVID-19." (PMID 36700209, 2022). "The ratios of IL-12/IL-4, IL-12/IL-10, IL-12/IL-5, IL-12/IL-9, IL-2/IL-10, and IL-2/IL-9 were substantially higher in COVID-19 ICU patients compared with HC subjects (≈5660-, 5333-, 2100-, 600-, 69-, and 24-fold differences, respectively)." (PMID 36363785, 2022). "Nevertheless, in the present study, IFN-γ, IL-4, IL-5, IL-6, and IL-10 were the only cytokines elevated in patients with COVID-19." (PMID 34987205, 2022). "In support, IL-4, IL-5, and IL-10 have previously been shown to increase over the course of disease in patients with severe COVID-19, suggesting an extensive upregulation of the adaptive immunity during COVID-19." (PMID 34987205, 2022).
COVID-19 (continued). "IL-5 levels and eosinophil numbers have been reported to be systemically elevated in severe COVID-19 patients." (PMID 35145069, 2022). "Immune profiling of severe COVID-19 patients has identified a complex pattern of cytokines including granulocyte macrophage-colony stimulating factor (GM-CSF) and interleukin (IL)-5, which are significant mediators of viral-induced hyperinflammation." (PMID 35145069, 2022). "The ratios of IFN-γ/IL-4, IL-12/IL-4, IFN- γ/IL-9, TNF-α/IL-4, IFN- γ/IL-5 and IL-12/IL-9 were lower ((≈30-, 11-, 8, 4-, 4-, and 3- fold differences respectively) in COVID-19 ICU patients as compared to HC subjects." (PMID 36363785, 2022). "An increase in serum levels of the Th2 cytokines IL-5 and IL-9 has been reported in COVID-19 ICU patients compared to HC." (PMID 36363785, 2022). "On the other hand, the production of TH2 cytokines (IL-4 and IL-5) and IL-10 was poor or negligible in both post-COVID-19 patients and vaccinated subjects." (PMID 35744768, 2022). "These cell types are also responsible for the pro-inflammatory state observed in COVID-19, and this is consistent with the higher levels of IL-1β, IP-10 and IL-5 observed in the critical COVID-19 group compared to the septic shock group." (PMID 36008932, 2022). "Aiming at finding discriminant oral cytokines for COVID-19 status, we employed volcano plot and VIP plot, finding out seven COVID-19-related discriminant cytokines (IL-6, IL-5, GCSF, IL-2, TNF-α, GMCSF, and INF-γ), while only one (IL-12p70) for controls." (PMID 34394024, 2021). "In contrast, COVID-19 was distinguished by a lymphocyte T cytokine response, as reflected by an increase in IL-2, IL-4, IL-5, IL-7, IL-13, IL-17, and soluble CD40L (sCD40L)." (PMID 35111777, 2021). "Nevertheless, IL-4, IL-5, and IL-13 displayed a trend toward an increase in the clinical scenario of severe COVID-19, and a reason for the interest is the importance of IL-5 to predict mortality, with a predictive value of around 0.73." (PMID 33767626, 2021). "A significantly higher proportion of COVID-19 convalescent individuals presented with increased IL-5, IL-6, and IL-1β levels." (PMID 34234102, 2021). "At baseline, we found higher levels of blood Th2 inflammatory cytokines (IL-5 and IL-13) in the blood of COVID-19 patients compared to controls." (PMID 33767713, 2021). "Among the severe asthmatic group with COVID-19, the majority were treated with anti-IL5 drugs (71%), with a minority with anti-IgE (29%)." (PMID 33767626, 2021). "In the COVID-19 placentas, some studies observed elevated IL-5 levels as well as decreased IL-7 and TNF-related apoptosis-inducing ligand levels." (PMID 35071136, 2021). "When we analyzed the median proportion of selected cytokines levels (pg/mL) such as: IL-1β, IL-4, IL-5, IL-6, IL-8, IL-10 and TNFα, we observed significant difference between severe COVID-19 and critical COVID-19 patient only for IL-6 level." (PMID 34064802, 2021). "In our study, we found that most of the cytokines recovered in the convalescent individuals except that a significantly higher proportion of COVID-19 convalescent individuals presented with elevated IL-5, IL-6, and IL-1β levels." (PMID 34234102, 2021). "A large number of patients with COVID-19 present a decreased lymphocytes count, and Th2-subtype lymphocytes are responsible for the production of IL-5, which stimulates the activation and the production of eosinophils." (PMID 33291791, 2020). "Also, in PLWH/COVID-19, serum levels of a different set of interleukins (IL-5, IL-6, IL-9, and IL-15) and chemokine CXCL10 were upregulated." (PMID 41516165, 2025). "In PLWH/COVID-19, elevated IL-6, IL-5, IL-9, and IL-15 interleukins compared to COVID-19-only could induce a strong immune response in these patients." (PMID 41516165, 2025).